RN7SKP194 (RN7SK pseudogene 194)
Gene: Miscellaneous RNA gene on chromosome X (96,410,432 to 96,410,782, reverse strand). Ensembl gene ENSG00000223260.
Homologues: Orthologues: chimpanzee 7SK (85% identical). Paralogues in human: RN7SKP240 (63% identical), RN7SKP90 (63% identical), 7SK (62% identical), RN7SKP162 (62% identical), RN7SKP3 (62% identical), RN7SKP33 (62% identical), RN7SKP249 (62% identical), RN7SKP192 (61% identical), RN7SKP217 (61% identical), RN7SKP225 (61% identical), RN7SKP133 (61% identical), RN7SKP250 (61% identical), and 283 more.